RNU7-140P (RNA, U7 small nuclear 140 pseudogene)
Gene: Small nuclear RNA gene on chromosome 19 (10,551,033 to 10,551,092, reverse strand). Ensembl gene ENSG00000238364.
Homologues: Orthologues: macaque U7 (90% identical). Paralogues in human: U7 (88% identical), RNU7-10P (87% identical), RNU7-172P (87% identical), RNU7-138P (85% identical), RNU7-2P (85% identical), RNU7-48P (85% identical), RNU7-55P (85% identical), RNU7-79P (85% identical), RNU7-124P (83% identical), RNU7-167P (83% identical), RNU7-183P (83% identical), RNU7-47P (83% identical), and 143 more.